ADAMTS13 (ADAM metallopeptidase with thrombospondin type 1 motif 13)
Diseases named in the same sentence as ADAMTS13 in open-access papers (continued):
Sharing a sentence is not in itself a finding about the gene and the disease.
infarct (2 papers, 2013 to 2025). "In our group, ADAMTS13:Ag was negatively correlated with the presence of cerebral silent infarcts and with infarct lesion dimension." (PMID 24205317, 2013). "ADAMTS-13 and t-PA:Ag are involved in the development of cerebral silent infarcts." (PMID 24205317, 2013).
influenza (2 papers, 2018 to 2021). An acute viral infection of the respiratory tract, occurring in isolated cases, in epidemics, or in pandemics; it is caused by serologically different strains of viruses (influenzaviruses) designated A, B, and C, has a 3-day incubation period, and usually lasts for 3 to 10 days. "Influenza is commonly associated to TTP, and cases where ADAMTS13 autoantibodies were developed following influenza infection have been described." (PMID 34858410, 2021). "The mechanism leading to the rise of anti-ADAMTS13 and other autoantibodies by influenza and influenza vaccines warrants additional research." (PMID 28884355, 2018). "The only exception is with Influenza, where a computational analysis was undertaken to assess if there are any sequences of the Influenza proteome that may resemble any part of the ADAMTS13 sequence and serve as cross-reactive T-cell epitopes." (PMID 34858410, 2021).
kidney injury (2 papers, 2016 to 2025). Trauma to the kidney. "We also detected elevated levels of anti-ADAMTS13 and anti-vWF antibodies in MHTN related kidney injury." (PMID 27278520, 2016).
malignant hypertension (2 papers, 2023 to 2026). Severe hypertension that is characterized by rapid onset of extremely high blood pressure and hypertension-mediated organ damage. "ADAMTS13 activity remains preserved in malignant hypertension TMA, while a severe deficiency (<10%) is diagnostic of TTP." (PMID 41236470, 2026). "Further evaluation, including preserved ADAMTS13 activity and the context of hypertensive retinopathy, supported malignant hypertension–induced TMA." (PMID 41236470, 2026).
melanoma (2 papers, 2008 to 2017). A malignant, usually aggressive tumor composed of atypical, neoplastic melanocytes. "The related metalloproteases ADAM9 (GeneID: 8754) and ADAMTS13 are upregulated in primary melanoma tumors and in melanoma cell lines, respectively." (PMID 18454205, 2008). "The role of VWF and its cleaving protease ADAMTS13 in melanoma metastasis is much less clear." (PMID 29152610, 2017).
neuropathy (2 papers, 2023). A disorder affecting the nervous system that manifests with pain, tingling, numbness, and/or muscle weakness. "ADAMTS-13 and HMGB1 are valuable biomarkers for disease risk assessment, estimating host neuropathy following T. multiceps (c." (PMID 37863934, 2023).
Pancreatic Cancer (2 papers, 2019 to 2025). "The ADAMTS‐13/VWF ratio was lowest in those with lung, colorectal and pancreatic cancers." (PMID 31294335, 2019).
Pancytopenia (2 papers, 2024 to 2026). An abnormal reduction in numbers of all blood cell types (red blood cells, white blood cells, and platelets). "The blood analysis showed pancytopenia (platelets 32 × 103/μL, leukocytes 4.31 × 103/μL, hemoglobin 8.8 g/dL), elevated D-dimer (20.3 mg/L), and decreased ADAMTS-13 activity (30%)." (PMID 39063619, 2024). "The analysis showed progressive pancytopenia (platelets 59 × 103/μL, leukocytes 3 × 103/μL, hemoglobin 9 g/dL) and decrease in ADAMTS13 activity (39%)." (PMID 39063619, 2024).
Portal vein thrombosis (2 papers, 2023 to 2024). Thrombosis of the portal vein and/or its tributaries, which include the splenic vein and the superior and inferior mesenteric veins. "ADAMTS13 activity was independently predictive for (i) portal vein thrombosis (PVT) and (ii) hepatic decompensation or liver-related death." (PMID 37605068, 2023).
rheumatoid arthritis (2 papers, 2025). A chronic, systemic autoimmune disorder characterized by inflammation in the synovial membranes and articular surfaces. "Severe ADAMTS13 deficiency has been predominantly detected in patients with SLE and rheumatoid arthritis (RA); however, systemic sclerosis, polymyositis, sarcoidosis, autoimmune thyroiditis, and Reynaud phenomenon have all been variously described in association with iTTP." (PMID 40136473, 2025).
Shock (2 papers, 2013 to 2020). The state in which profound and widespread reduction of effective tissue perfusion leads first to reversible, and then if prolonged, to irreversible cellular injury. "A high vWF:Ag/ADAMTS13 ratio has been associated previously with the development of TMA, higher severity of shock, degree of organ failure, and worse outcomes in patients with septic shock." (PMID 32122366, 2020).
Sjögren's syndrome (2 papers, 2020 to 2021). "Of the 36 patients with acquired ADAMTS13 deficiency, TTP was considered SLE-related in 10, Sjögren’s syndrome-related in three, undifferentiated connective tissue disease (UCTD)-related in two, malignancy-related in three, and primary in 18 patients." (PMID 32859237, 2020).
systemic sclerosis (2 papers, 2022 to 2023). A chronic disorder, possibly autoimmune, marked by excessive production of collagen which results in hardening and thickening of body tissues. "On the other hand, non-inhibitory anti-ADAMTS13 antibodies and low protease activity can be detected in SLE and systemic sclerosis patients without active iTTP." (PMID 36576539, 2023).
von Willebrand disease type 2B (2 papers, 2012 to 2014). A subtype of type 2 VWD characterized by a bleeding disorder associated with an increase in the affinity of the Willebrand factor (von Willebrand factor; VWF) for platelets. "Mutation and ADAMTS13-dependent modulation of disease severity in a mouse model for von Willebrand disease type 2B." (PMID 22616016, 2012). "A previous study showed similar results as ADAMTS13 increased after exercise in patients with von Willebrand disease type 2B." (PMID 24626470, 2014).
acute cholangitis (1 paper, 2023). Cholangitis that is both sudden in onset and of a relatively short duration. "Our previous study reported that VWF:Ag/ADAMTS13:AC was associated with the severity of acute cholangitis and DIC score." (PMID 36829443, 2023).
acute lymphoblastic leukemia (1 paper, 2022). Leukemia with an acute onset, characterized by the presence of lymphoblasts in the bone marrow and the peripheral blood. "With regards to hematological malignancies, there is evidence to suggest that ADAMTS13 levels are reduced in patients with acute lymphoblastic leukemia (ALL), and that lower levels are correlated with high-risk ALL and increased inflammation." (PMID 35327035, 2022).
acute myeloid leukaemia (1 paper, 2025). "Low levels of the enzyme ADAMTS13 and elevated inflammatory markers such as interleukin-6 (IL-6) are associated with worse outcomes in patients with acute myeloid leukaemia (AML)." (PMID 40671161, 2025).
acute pancreatitis (1 paper, 2020). An acute inflammatory process that leads to necrosis of the pancreatic parenchyma. "Proinflammatory mediators released during the systemic inflammatory response seen in acute pancreatitis can promote VWF activity and inhibit ADAMTS13 activity." (PMID 32642381, 2020).
Allergy (1 paper, 2025). An allergy is an immune response or reaction to substances that are usually not harmful. "In patients with recurrent or severe allergy to FFP, plasma-derived factor VIII concentrates, which contain trace amounts of ADAMTS-13, have been utilized, but the impact on ADAMTS-13 activity is marginal." (PMID 39995752, 2025).
aneurysm (1 paper, 2021). Bulging or ballooning in an area of an artery secondary to arterial wall weakening. "Both copies of ADAMTS13 gene were described with the rs2301612 variant, previously detected in patients with aneurysms." (PMID 34502390, 2021). "Additionally, copies of ADAMTS13 gene were described with the rs2301612 variant defined before in patients with aneurysms, which is a benign variant that does not decrease ADAMTS13 activity." (PMID 34502390, 2021).
aortic aneurysm (1 paper, 2014). A ruptured aneurysm located in the wall of the proximal portion of the descending aorta proceeding from the arch of the aorta. "Since preoperative acceleration of fibrinolysis was recognized in the current study, degradation of ADAMTS13 by thrombin and/or plasmin could partly explain the decreased level of ADAMTS13 activity in patients with aortic aneurysm." (PMID 25960882, 2014).
arteriovenous malformations (1 paper, 2023). "The corresponding dominating mechanism is the excessive proteolysis of HMWM-vWFs by ADAMTS-13 in the context of the high shear stress related to stenotic valves, which not only predisposes patients to bleed but also induces submucosal arteriovenous malformations in the digestive tract." (PMID 37430321, 2023).
Ascites (1 paper, 2022). Accumulation of fluid in the peritoneal cavity (between the layers of the peritoneum that lines the abdomen). "We speculate that the development of hepatic encephalopathy, HRS, and ascites is associated with platelet microthrombi formation through an imbalance between ADAMTS13 enzyme and VWF substrate." (PMID 35407443, 2022). "Previous work has shown that a decrease in ADAMTS13:AC and increase in VWF:Ag levels are associated with hepatic encephalopathy, HRS, and ascites." (PMID 35407443, 2022).
biliary atresia (1 paper, 2011). A rare, biliary tract disease characterized by progressive obliterative cholangiopathy of the intra- and extrahepatic bile ducts, occurring in the embryonic/ perinatal period, leading to severe and persistent neonatal jaundice and acholic stool. "In 2000, we demonstrated that a decreased plasma ADAMTS13 : AC in patients with cirrhotic biliary atresia can be fully restored after liver transplantation, indicating that the liver is the main organ producing ADAMTS13." (PMID 21994870, 2011).
brain injury (1 paper, 2020). Acute and chronic (see also brain INJURIES, CHRONIC) injuries to the brain, including the cerebral hemispheres, CEREBELLUM, and brain STEM. "A beneficial effect of ADAMTS-13 on trauma-induced coagulopathy is in line with findings in a model of traumatic brain injury, in which ADAMTS-13 led to reduction in consumption coagulopathy in ADAMTS-13 depleted mice." (PMID 33336308, 2020).
brain tumor (1 paper, 2022). "In the high risk group, one of the 10 patients, a 38-year-old woman with ADAMTS13 activity level of >10%, initially presented with intermittent headache; the image showed brain tumor with hemorrhage." (PMID 35615090, 2022). "One patient with a brain tumor and a PLASMIC score of 6 did not have severe ADAMTS13 activity of ≤10%." (PMID 35615090, 2022).
breast adenocarcinoma (1 paper, 2025). "In our second case, we demonstrated a patient with low ADAMTS13 activity and anti-ADAMTS13 antibodies with proven breast adenocarcinoma, so vigorously searching for possible tumours should be performed even in cases with low ADAMTS13." (PMID 40217615, 2025).
cerebral aneurysms (1 paper, 2023). "The other investigation found that the rs2301612 SNP, known to be a key determinant of plasma ADAMTS13 levels, is associated with cerebral aneurysms due to abnormal arterial wall remodeling." (PMID 36980889, 2023). "The rs2301612 SNP in the ADAMTS13 gene is associated with cerebral aneurysms, possibly via altered arterial wall remodeling." (PMID 36980889, 2023).
cholestasis (1 paper, 2016). Impairment of the bile flow caused by obstruction within the liver, or outside the liver in the bile duct system. "Moreover, experimental cholestasis and steatohepatitis elevate plasma ADAMTS13 levels, while partial hepatectomy in humans has the opposite effect." (PMID 27485105, 2016).
cognitive decline (1 paper, 2018). "Although the mechanisms underlying these observations are unknown, it is conceivable that ADAMTS13 has other, yet unidentified proteolytic activity, or competes/ interacts with glucose or currently unknown protein(s) to contribute to cognitive decline." (PMID 29615758, 2018).
complement deficiency (1 paper, 2011). A genetic deficiency of any of the component of the complement system (including the classical, alternative, and terminal pathway components), that can either be acquired or inherited. "In TTP-HUS caused by either ADAMTS-13 or by complement deficiency, plasma exchange therapy is the treatment of choice." (PMID 22206706, 2011).
coronary thrombosis (1 paper, 2020). Coagulation of blood in any of the coronary vessels. "Concentration of plasma ADAMTS13 decreases when vWF level increases during acute formation process of coronary thrombosis." (PMID 32293292, 2020).
cyst (1 paper, 2023). A sac-like closed membranous structure that may be empty or contain fluid or amorphous material. "The most striking finding of this study is that the expressions of ADAMTS-13 and HMGB1 are significantly increased in the lesioned areas and the areas close to the cyst." (PMID 37863934, 2023). "The most striking finding of this study is that the expressions of ADAMTS-13 and HMGB1 were significantly increased in the lesioned areas and the areas close to the cyst." (PMID 37863934, 2023).
demyelination (1 paper, 2020). "Moreover, we demonstrated that exogenous ADAMTS13 treatment suppressed the development and severity of EAE mice by alleviating demyelination and the inflammatory response in the spinal cord." (PMID 32075652, 2020).
End Stage Liver Disease (1 paper, 2024). Final stage of a liver disease when the liver failure is irreversible and LIVER TRANSPLANTATION is needed. "ADAMTS-13 activity predicts the cumulative survival of patients with LC in comparison with the CPS and the model for end-stage liver disease score (MELD score)." (PMID 38473925, 2024).
endometriosis of the ovary (1 paper, 2023). "In summary, the evidence suggests that ADAMTS13 may have a negative causal relationship with endometriosis of the ovary, pelvic peritoneum, and uterus, while vWF may have a positive causal relationship with endometriosis of the ovary and pelvic peritoneum." (PMID 37226166, 2023).
Evans syndrome (1 paper, 2023). "Certain patients diagnosed with Evans syndrome are direct Coombs–negative, and this group may include individuals who should be diagnosed with TTP based on severely decreased ADAMTS13 activity." (PMID 37689812, 2023).
experimental autoimmune encephalomyelitis (1 paper, 2020). An autoimmune demyelinating disease of the central nervous system that is produced experimentally in animals by the injection of homogenized brain or spinal cord in Freund's adjuvant. "In the present study, we have determined the role of ADAMTS13 in the disease progression of MS using a mouse model of experimental autoimmune encephalomyelitis (EAE)." (PMID 32075652, 2020).
fibrosis (1 paper, 2018). the formation of excess fibrous connective tissue in an organ or tissue in a reparative or reactive process. "In this context, ADAMTS13 was shown to correlate with severity of fibrosis and its activity was impaired in patients with mild to moderate fibrosis, as a sign of consecutive activation and secretion of ADAMTS13 proteinase." (PMID 30429491, 2018). "Nevertheless, due to the constant stimulus and thereby exhaustion of HSC, ADAMTS13-AC was significantly reduced in patients with severe fibrosis/cirrhosis." (PMID 30429491, 2018).
fungal infections (1 paper, 2017). "Taken together, this set of data clearly shows that ADAMTS-13 deficiency is associated with an increased susceptibility to fungal infections resulting in a higher mortality rate, apparently leading to an uncoordinated inflammatory response along with a decreased ability to clear the fungal burden." (PMID 28775254, 2017).
gastric cancer (1 paper, 2025). A primary or metastatic malignant neoplasm involving the stomach. "A study investigating gastric cancer cells reported that the deletion of a downstream region of the ABO gene altered the expression of nearby genes, including a reduction in ADAMTS13 transcription." (PMID 41311061, 2025).
hemorrhagic stroke (1 paper, 2020). A stroke caused by a bleed on the brain. "In addition, preclinical studies of ADAMTS13 have shown promise in reducing the inflammatory response of various neurological disease models such as ischemic and hemorrhagic stroke." (PMID 32075652, 2020). "For example, studies have reported that intraventricular administration of VWF leads to increased BBB permeability and that ADAMTS13 blocked BBB opening in both ischemic and hemorrhagic stroke mice." (PMID 32075652, 2020).
infective endocarditis (1 paper, 2025). Infective endocarditis (IE) is an infection of the inner lining of the heart chambers (endocardium) and valves. "Using heparin and ADAMTS13 to reduce ULVWF production could open up new ways to treat infective endocarditis." (PMID 40422904, 2025).
intracerebral hemorrhage (1 paper, 2019). A cerebrovascular disorder characterized by bleeding into one or both cerebral hemispheres including the basal ganglia and the cerebral cortex. "It has been reported that recombinant ADAMTS13 (rADAMTS13), when injected into mice before ischemia reperfusion, significantly reduced the infarct volume and improved prognosis without eliciting intracerebral hemorrhage." (PMID 31379722, 2019).
invasive carcinoma (1 paper, 2025). A carcinoma that is not confined to the epithelium, and has spread to the surrounding stroma. "Notably, ADAMTS13 expression increased progressively from sparse staining in normal ducts and low‐grade precursor lesions to ubiquitous positivity in high‐grade precursor lesions, invasive carcinoma, and metastases." (PMID 41211185, 2025).
iron overload (1 paper, 2020). "P34 had UH and iron overload, and variations in 3 genes: a homozygous p.H63D variation in HFE, which may contribute to iron overload even though its implication is not totally clear, a heterozygous ABCG8 VUS and 2 heterozygous ADAMTS13 VUS." (PMID 32641076, 2020).
leptospirosis (1 paper, 2017). A contagious bacterial infection caused by spirochetes of the genus Leptospira. "Cases of leptospirosis-associated TTP have also been described, including that with severely reduced ADAMTS13 activity." (PMID 28934202, 2017). "ADAMTS13 activity levels were decreased in leptospirosis patients and were lowest in bleeders." (PMID 28934202, 2017).
leukaemia (1 paper, 2025). "IL-6 produced by leukaemia cells suppresses ADAMTS13 activity and impairs hematopoietic differentiation." (PMID 40671161, 2025).
lymphoma (1 paper, 2024). A malignant (clonal) proliferation of B- lymphocytes or T- lymphocytes which involves the lymph nodes, bone marrow and/or extranodal sites. "Rituximab is given at a weekly dose of 375 mg/m2 over four weeks, based on lymphoma management guidelines, although further immunosuppression is guaranteed in failed ADAMTS13 activity level normalization." (PMID 39125707, 2024).
Macrothrombocytopenia (1 paper, 2025). "Variants in genes not typically linked to macrothrombocytopenia, like ADAMTS13 and MASTL, were also found." (PMID 40941697, 2025).
metastatic disease (1 paper, 2022). "While ADAMTS13 levels decrease in a range of disseminated cancers, ADAM28 expression is increased with advanced metastatic disease, likely due to a local tumor-induced expression of ADAM28." (PMID 35327035, 2022). "A more recent study evaluated this concept further and found that reduced ADAMTS13 activity and higher VWF antigen levels are associated with metastatic disease and reduced event-free survival, independent of age, gender, and stage-independent predictors of mortality in colorectal cancer." (PMID 35327035, 2022).
Miscarriage (1 paper, 2014). A pregnancy that ends at a stage in which the fetus is incapable of surviving on its own, defined as the spontaneous loss of a fetus before the 22th week of pregnancy. "Anti-ADAMTS13 antibodies resulted to be invariably present in either group of cases, with median anti-ADAMTS13 IgG levels of 4% (range 3–7.5%) in women with gravidic TTP and 2% (range <1.18-4.4%) in the miscarriage group." (PMID 25431165, 2014).